BAP1 (BRCA1 associated deubiquitinase 1)
Diseases named in the same sentence as BAP1 in open-access papers (continued):
Sharing a sentence is not in itself a finding about the gene and the disease.
melanoma (continued). "In contrast, BAP1 PV carriers affected by melanoma—both cutaneous and uveal—exhibit increased risk of metastasis, suggesting a shorter survival rate." (PMID 35885614, 2022). "In fact, a number of HR-DDR genes, such as BRCA1/2, FANCA and BAP1, are associated with genetic syndromes that increase predisposition to cancers such as melanoma." (PMID 34572747, 2021). "The mutation in BAP1 was captured in the melanoma, as well as mutations in KMT2A (a known cancer driver mutation in melanoma) and TIAM1 (a gene involved in the RAC1 signaling pathway affecting cell shape and migration)." (PMID 35052351, 2021). "Identified cases were screened for BAP1 loss using immunohistochemistry; while patients with melanoma and clear cell RCC were screened for MITF p.E318K alterations." (PMID 34767027, 2021). "Given the patient's prior history of melanoma and of heterozygous BAP1 gene mutation, histopathological and molecular analysis was performed on the lesion, revealing a diffuse loss of BAP1 expression and multiple chromosomal aberrancies." (PMID 34646590, 2021). "Altogether a diagnosis was rendered of melanoma developing in the context of a melanocytic nevus with associated BAP1 genomic loss (melanoma ex-“BAPoma”)." (PMID 35052351, 2021). "To explore the expression profiles of a full spectrum of BAP1-inactivated lesions, here we performed RNA sequencing on three lesions from a young patient with a nevus, an atypical tumor, and a melanoma with BAP1 loss." (PMID 35052351, 2021). "Established increased risk of renal cancer and/or melanoma is observed with BAP1 mutations responsible for BAP1-TPDS, PTEN-AKT1/2-PIK3CA induced PTEN-opathies, as well as mTOR signaling syndromes such as TSC1/2 tuberous sclerosis complex." (PMID 34067022, 2021). "BAP1 (BRCA1-associated protein 1) is another well-described gene associated with melanoma development." (PMID 34638397, 2021). "Common putative risk genes for RCC and melanoma – BAP1, MITF, CDKN2B – suggest that similar pathways are disrupted in both disorders; however, individual variant risks should be evaluated when shared genetic background is taken into account." (PMID 33051548, 2020). "BAP1 is a tumor suppressor gene with a poorly understood mechanism in melanoma development but has been implicated as a deubiquitinase of cell cycle genes." (PMID 32429485, 2020). "The enrollment of 22 melanoma patients with atypical Spitz nevi with relatives developing BAP1-related tumors can explain an increased prevalence of BAP1 mutation carriers in this Italian study." (PMID 33050356, 2020). "The intermediate risk‐group melanomas had either BAP1 (4/13, 30.7%) or SF3B1 (5/13, 38.5%) mutations." (PMID 31025552, 2019). "Recent reports have associated the loss of BAP1 expression with reduced melanocytic differentiation in melanomas." (PMID 28404968, 2017). "Recent studies revealed that BAP1 mutations are closely associated with the onset and prognosis of melanoma and other malignancies." (PMID 28404968, 2017). "Germline mutations in BAP1 are rare, being present in <1% of the population-ascertained melanoma cases in the UK." (PMID 28062663, 2017). "Here we report germline mutations of the BAP1 gene in a sample of 1977 melanoma patients and 754 controls ascertained from the UK population as part of the Leeds Melanoma Case-Control Study." (PMID 28062663, 2017). "Two of these three probands carrying BAP1 loss-of-function variants also had melanomas with histopathological features suggestive of a germline BAP1 mutation." (PMID 28062663, 2017). "We hope that this work presents a framework for considering the management of individuals found to carry germline BAP1 mutations in the context of sporadic melanoma." (PMID 28062663, 2017). "The knockdown of BAP1 gene in melanoma cell harboring undetectable BAP1 mutation developed a rounded epithelioid morphology and grew as multicellular nonadherent spheroids, paralleled with the gene expression profile shifting to a metastasizing pattern." (PMID 28544818, 2017).
melanoma (continued). "BAP1 is a tumor suppressor that has been associated with the outcome of melanomas and other malignancies." (PMID 28404968, 2017). "As such, we sought to determine the contribution of BAP1 variants to sporadic melanoma, and here we present the most comprehensive such analysis to-date." (PMID 28062663, 2017). "This study therefore suggests that complete loss-of-function germline BAP1 mutations underlie susceptibility to cutaneous melanoma in ∼0.2% of the population-ascertained melanoma cases in the UK." (PMID 28062663, 2017). "In melanoma-dominant or melanoma-subordinate pedigrees or in individuals carrying a BAP1, CDK4, CDKN2A, MITF, or POT1 mutation, individuals should be educated on the importance of melanoma prevention and early detection." (PMID 28283772, 2017). "We recently showed that BAP1 loss causes increased histone H2A ubiquitination in melanoma cells and melanocytes, and this hyperubiquitination was reversed by treatment with HDAC inhibitors, which inhibit BMI1." (PMID 23915344, 2013). "In this study, we performed a comprehensive screen of BAP1 in melanoma patients to date and our findings point to an important role for BAP1 in melanoma predisposition." (PMID 22545102, 2012). "In aggregate, there were 6 distinct novel germline BAP1 variants out of 300 melanoma patients analyzed." (PMID 22545102, 2012). "High-risk molecular features include Class 2 gene expression profile (GEP), expression of PRAME (preferentially expressed antigen in melanoma), BAP1 mutations leading to loss of BAP1 function, loss of heterozygosity on chromosome 3, and gain of chromosomes 1q, 6p, or 8q." (PMID 41514630, 2025). "This may be related to the loss of the tumor suppressor gene, BAP-1, which may increase melanoma invasiveness and potential for metastasis." (PMID 40867312, 2025). "However, since most of the families carrying a BAP1 germline mutation present at least one melanoma case, the high penetrance for familial melanoma seems to be confirmed." (PMID 40869905, 2025). "In melanoma, BAP1 mutations promote tumor cell glycolysis, leading to increased lactate production." (PMID 39587076, 2024). "BAP1 is commonly mutated in other neoplasms, such as malignant mesothelioma and melanoma." (PMID 39435876, 2024). "There are data to suggest that self-examination increases the rate of diagnosis of early lesions in families with increased risk of melanoma that may be relevant to BAP1 GPV carriers." (PMID 37607989, 2023). "Question 3: Which other type of melanoma is associated with BAP1 gene abnormalities?" (PMID 38090659, 2023). "Proband MM981 (PD-578) carries the p.Trp202* PV in BAP1, a previously unknown nonsense variant, and his melanoma shows loss of protein expression." (PMID 35885614, 2022). "IHC of two different melanomas of the proband showed loss of nuclear BAP1 protein expression." (PMID 35885614, 2022). "However, melanoma tissue is routinely examined for monosomy 3 and, if proven, for somatic BAP1 variants." (PMID 33919815, 2021). "Loss of BAP-1 expression in malignant melanoma may be also helpful in discriminating benign from malignant melanocytic lesions." (PMID 34206844, 2021). "One drawback of the use of BAP1 IHC is that BAP1 mutation and thus BAP1 protein loss may occur in other metastatic pleural malignancies, such as lung, breast, melanoma, and kidney tumors." (PMID 33014860, 2020). "However, the exact mechanism of BAP1 mutations that promote melanoma genesis is yet to be elucidated." (PMID 31717496, 2019). "Furthermore, the occurrence of UM and ≥1 non-melanoma BAP1-TPDS-associated tumors led to the suspicion of an underlying genetic disease in four families (18%)." (PMID 31382694, 2019). "Currently, the National Comprehensive Cancer Network (NCCN) reports that BAP1 testing may be warranted in specific cases, along with testing for other melanoma-predisposing genes like CDK4, MITF and TERT." (PMID 31382929, 2019).
melanoma (continued). "We next asked if a histopathological analysis of the primary melanoma in the proband (indicated by an arrow in each pedigree) had features reported in the literature as being suggestive of the atypical melanocytic tumours of germline BAP1 mutation carriers." (PMID 28062663, 2017). "Mutation in BAP1 has been correlated with the cell type of melanoma in many studies." (PMID 28404968, 2017). "More importantly, some affected patients developed uveal or cutaneous melanomas, demonstrating the role of BAP1 mutations in conferring increased melanoma risk 63.Therefore, the mutations of BAP1 contribute to not only melanoma tumorigenesis, but also melanoma metastasis." (PMID 28544818, 2017). "We sequenced 1,977 melanoma cases and 754 controls, identifying a total of 30 BAP1 variants." (PMID 28062663, 2017). "Overall, less than ∼0.2% of melanoma cases had identifiable loss-of-function BAP1 variants." (PMID 28062663, 2017). "Primary melanomas in 2/3 probands with clear loss of function mutations demonstrated some of the histopathological features described in melanocytic lesions associated with a BAP1 mutation." (PMID 28062663, 2017). "Mutations in the BRCA1 associated protein-1 (ubiquitin carboxy-terminal hydrolase) (BAP1) gene on chromosome 3p21 may be the reason melanoma cells lose one copy of chromosome 3." (PMID 24049435, 2013). "Gene Set Enrichment Analysis of transcripts that were deregulated in cells depleted of BAP1 revealed enrichment of gene sets associated with metastasis in melanoma, prostate, lung, and pancreatic cancer, suggesting a more general role for BAP1 loss in cancer progression." (PMID 23915344, 2013). "Looking ahead, one could envision using COMMON features (eg. nevoid melanomas and NEMMPs) in order to clinically identify potential BAP1 mutation carriers, who may benefit from targeted screening for high-risk ocular melanomas." (PMID 22545102, 2012). "Observations supporting this concept include the apparent growth advantage of the BAP1‐inactivated clone over background nevus, the increased risk of cutaneous melanoma in patients with germline BAP1 mutations, and the reported cases of BAP1‐inactivated melanomas." (PMID 39976080, 2025). "Furthermore, hereditary melanoma has been associated with germline mutations in high-risk melanoma susceptibility genes (CDKN2A, CDK4, TERT, POT1), polymorphisms in intermediate-risk melanoma susceptibility genes (BAP1, ACD, TERF2IP, MC1R and MITF), and germline missense substitutions in MITF." (PMID 32276436, 2020). "Functionally, we previously showed that BAP1 depletion reduced melanoma cell viability and tumorigenicity, paradoxical to its putative suppressor role." (PMID 41480773, 2026). "We subsequently depleted BAP1 in 3 melanoma cell lines and observed marked reductions in the protein levels of Sox10 and Mitf, cellular growth, and cellular pigmentation." (PMID 41480773, 2026). "While BAP1 functions as a putative melanoma tumor suppressor, its full role in melanocyte survival and proliferation is poorly understood." (PMID 41480773, 2026). "Here we describe 19 BIMs and five BAP1‐inactivated melanomas with attention to their histologic features, copy number changes by SNP microarray analysis, and clinical outcomes." (PMID 39976080, 2025). "Here we report the features of 24 BAP1‐inactivated melanocytic tumours including 19 BAP1‐inactivated melanocytomas (BIMs) and five BAP1‐inactivated melanomas." (PMID 39976080, 2025). "Other high- and moderate-penetrance genes—such as BAP1, POT1, BRCA2, and TERT—were also included, reflecting an expanded institutional approach to hereditary melanoma risk assessment." (PMID 40863406, 2025). "Multigene panel testing, including genes like CDKN2A, CDK4, BAP1, POT1, ACD, and TERF2IP, enhances the detection of hereditary melanoma risk." (PMID 39941357, 2025).
melanoma (continued). "Although melanomas with BAP1 deletion have been reported, including those arising in BIMs or common acquired nevi, the vast majority of BIMs reported in series to date have had an indolent clinical course." (PMID 39976080, 2025). "Here we describe a series of BIMs and BAP1‐inactivated melanomas for which SNP microarray analysis was performed as an ancillary diagnostic test." (PMID 39976080, 2025). "The first such patient had a personal history of BAP1‐inactivated cutaneous melanoma, as well as a family history of early onset melanoma." (PMID 39976080, 2025). "The median number of CNAs in the BAP1‐inactivated melanomas was seven (range 6–10) compared to two (range 0–6) in indolent cases." (PMID 39976080, 2025). "The main germline molecular alterations related to the risk of developing melanoma are alterations in the CDKN2a, CDK4, MC1R, BAP1, TERT, MITF, PTEN genes." (PMID 40614549, 2025). "Here we report the clinical features, histopathologic findings, and chromosomal copy number data of 19 BAP1‐inactivated melanocytomas (BIMs) and compare their features to those of five BAP1‐inactivated melanomas." (PMID 39976080, 2025). "Although not fully diagnostic, a mitotic count of ≥3/mm2 and ≥6 CNAs support a diagnosis of BAP1‐inactivated melanoma." (PMID 39976080, 2025). "Genetic predisposition is significant as 5–12% of melanoma cases are familial and often linked to high-penetrance mutations in genes such as CDKN2A, BAP1, and MC1R involved in DNA repair, immune function, cell adhesion, transcription, and melanin production." (PMID 41283485, 2025). "Their results not only support the use of a multi-genes panel test in familial melanoma, but also suggests a pivotal role of BAP1 and MITF genes." (PMID 40869905, 2025). "Although not fully diagnostic, a mitotic count of ≥3/mm2 and ≥6 CNAs in the appropriate context is supportive of a diagnosis of BAP1‐inactivated melanoma." (PMID 39976080, 2025). "By elucidating the interaction between BAP1 and LDHA and the subsequent effects on lactate production in melanoma cells, this work provides insights into the mechanism of BAP1-mediated metabolic regulation." (PMID 39587076, 2024). "Other reported melanocytic tumors involving fusions of RAF1 include malignant melanoma, BAP1-inactivating melanocytoma, and congenital naevi." (PMID 38390852, 2024). "The diagnosis of BAP1-inactivated melanomas represents a clinical and histopathological challenge, requiring comprehensive analysis of morphology and sometimes molecular analysis in addition to immunohistochemistry." (PMID 38473375, 2024). "According to the experimental flow diagram show, after inoculation of B16F10 tumor cells into mice, we performed transcriptomic sequencing analysis (RNA-Seq) on mouse tumors to verify the specific effect of BAP1 on melanoma glycolysis in vivo." (PMID 39587076, 2024). "In melanoma, WWP1 mediates the K48-linked ubiquitination and degradation of KLF5, a process antagonized by oncogenic deubiquitinase BAP1." (PMID 38129384, 2023). "The proband carrying the GPV in the BAP1 gene (MH20) also showed an RHC variant of MC1R (R/0) and had multiple nevi, fair skin, and a history of sunburn in childhood, as well as multiple melanomas diagnosed at an early age." (PMID 37958811, 2023). "In our cohort, out of 115 patients referred to genetic counseling for melanoma, 25 tested positive (21.7%) for critical mutations: CDKN2A (n = 12), MITF (n = 3), BAP1 (n = 1), MC1R (n = 3), PTEN (n = 1), TYR (n = 2), OCA2 (n = 1), and SLC45A2 (n = 2)." (PMID 37568588, 2023). "In melanoma patients, the expression level of WWP1 was positively associated with good prognosis whereas the expression levels of KLF5 and BAP1 were found to be positively associated with poor prognosis." (PMID 36918822, 2023).
melanoma (continued). "Epithelioid cell type, monosomy 3 and 6p gain, and deletion of the BAP-1 gene are among the histopathologic and tumor-specific genetic abnormalities that are most important for melanoma-specific mortality prediction." (PMID 36793711, 2023). "Germline pathogenic variants (GPVs) in melanoma susceptibility genes CDKN2A, CDK4, and BAP1 are identified in up to 40%, 0.7%, and 1.0% of familial melanoma cases, respectively." (PMID 36876055, 2023). "Jia and colleagues found that BAP1 promotes melanoma migration and invasion by antagonizing WWP1-mediated KLF5 ubiquitination and degradation, suggesting that WWP1 plays a negative role in regulating invasion and migration in melanoma." (PMID 38129384, 2023). "A similar effect, accompanied by a reduction in cell invasion, was obtained in the established human melanoma cell lines LOX (ARID1A and BAP1 mutated)." (PMID 35563772, 2022). "Genetic predisposition accounts for nearly 10% of all melanoma cases and has been associated with a dozen moderate- to high-penetrance genes, including CDKN2A, CDK4, POT1 and BAP1." (PMID 35085295, 2022). "For familial melanomas, previous reports showed a prevalence of germline BAP1 PVs ranging from 20–30% for UM to <1% for CM." (PMID 35885614, 2022). "Although the melanoma cells showed a weak focal BAP1 nuclear expression at IHC, the DNA extracted from the FFPE tumor specimens revealed LOH in the tumor." (PMID 35885614, 2022). "We first looked at an extended list of high-risk genes predisposing to melanoma (ACD, CDKN2A, CDK4, POT1, TERF2IP, and TERT) or RCC (CDKN2B, FH, FLCN, MET, PBRM1, PTEN, SDHs, TSCs, and VHL) or both (BAP1 and MITF)." (PMID 34067022, 2021). "Approximately 40% of familial cases can be attributed to high penetrance melanoma susceptibility genes such as CDKN2A, CDK4 and BAP1." (PMID 34572747, 2021). "RNA sequencing was performed on three independent lesions spanning the morphologic spectrum: a benign nevus, an atypical tumor, and a melanoma arising from a pre-existing BAP1-inactivated nevus." (PMID 35052351, 2021). "In melanoma, the constitutively active, oncogenic form of BRAF (BRAFV600E) combined with BAP1 loss was seen in 67% of BAP1 tumor syndrome-associated lesions." (PMID 33483476, 2021). "For both the familial and sporadic lesions, prior studies found that only a minority of the BAP1-inactivated melanocytic lesions progress to melanoma, suggesting a relatively low malignant potential." (PMID 35052351, 2021). "We then wanted to explore which genes are progressively upregulated or downregulated from a benign BAP1-inactivated nevus to a BAP1-inactivated melanoma." (PMID 35052351, 2021). "Growing evidences show that BAP1 is frequently mutated in many human cancers to suggest BAP1 as a tumor suppressor; however, there are also a few studies reporting that BAP1 plays a role in promoting growth of melanoma and breast cancer." (PMID 33155366, 2021). "Our study possesses potential clinical significance by suggesting multiple therapeutic targets in patients with BAP1-inactivated melanoma, the treatment for whom is otherwise limited to conventional therapies." (PMID 35052351, 2021). "Our three patients carriers of a BAP1 pathogenic mutation that belonged to typical BAP1-tumor predisposition syndrome (TPDS) families with established increased co-susceptibility to RCC and melanoma." (PMID 34067022, 2021). "We describe an atypical, amelanotic melanoma in a 45-year-old male with a history of BAP1-TPDS and nodular melanoma." (PMID 34646590, 2021). "Less common melanoma susceptibly genes include CDKN2A/ARF, CDK4 (cyclin-dependent kinase 4), TERT, MITF (melanocyte inducing transcription factor), BAP1 (BRCA1 associated protein-1), and POT1 (protection of telomeres 1)." (PMID 34440462, 2021).